EZH2 (enhancer of zeste 2 polycomb repressive complex 2 subunit)
Diseases named in the same sentence as EZH2 in open-access papers (continued):
Sharing a sentence is not in itself a finding about the gene and the disease.
tumor (continued). "We examined protein expression in B, T, and PDX samples for CCND1, KI67, CD34, GPC3, YAP, and EZH2 to provide loose validation of different tumor clusters." (PMID 34497364, 2021). "The EZH2 gene mainly contributes to tumor development by promoting angiogenesis, silencing tumor suppressor genes and inhibiting the apoptosis of tumor cells." (PMID 34551671, 2021). "In summary, these data suggest a tumor-suppressive role of EZH2 under glucose deprivation conditions." (PMID 34671029, 2021). "The results from qPCR analysis indicated that the combination treatment significantly decreased ORC1 expression in both EZH2 wild-type and mutant tumor cells." (PMID 34503063, 2021). "The role of EZH2 gene in tumors, especially in tumor cell invasion and metastasis, has gradually become a research hotspot." (PMID 34604069, 2021). "EZH2 expression was low in three samples (<1.5% of positive tumor cells), intermediate in one sample (1.5% ≤ x ≤ 3% positive tumor cells), and high (>3% of positive tumor cells) in the two remaining cases." (PMID 34638497, 2021). "Now, our analysis has revealed a mixed prognostic ability for EZH2 dependent on immunogenic and angiogenic tumor properties." (PMID 34140011, 2021). "High levels of EZH2 had a direct effect on Notch expression and signaling in BCSCs in an independent behavior with the activity of EZH2 histone methyltransferase that led to the development of CSCs populations, and an increase in tumor initiation." (PMID 34051847, 2021). "The functional mutations in EZH2 occur frequently in both GCB-DLBCL and follicular lymphoma (FL), which downregulate tumor suppressor genes and promote the proliferation of tumor cells." (PMID 34503063, 2021). "As the master epigenetic regulator, EZH2 controls gene silencing through its mark H3K27me3 and it can alter the metabolic profile of tumor cells through the metabolism of glucose, lipids and amino acids, as demonstrated in recent studies." (PMID 34072826, 2021). "We previously reported that deletion or inhibition of Ezh2 in hematopoietic stem and progenitor cells (HSPCs) enhanced NK cell commitment and cytotoxicity against tumor cells." (PMID 34764950, 2021). "It is explained that EZH2 inhibition can enhance tumor cell Class I MHC expression in vivo including in highly resistant models." (PMID 35003090, 2021). "Consistent with the in vitro findings, inhibition of EZH2 using shEZH2 or UNC1999 resulted in a significant reduction in tumor volume and weight when treated with OXA." (PMID 33966039, 2021). "Our results show that the ZNF518B protein recruits the histone methyltransferases EZH2 and G9A on several tumour suppressor genes and the resulting repressive marks on histone H3 contribute to reducing the expression level of these genes." (PMID 33801071, 2021). "Alternative research has suggested that EZH2 inhibits the expression of tumor-suppressor genes by inducing H3K27me3." (PMID 34051847, 2021). "Due to EZH2 role in promoting the self-renewal of tumor cells, inhibiting them can prevent the formation of CSCs." (PMID 34051847, 2021). "SHR2554 exerted strong tumor suppressive activity in EZH2 mutant xenograft models SU-DHL-6 and PDX002, with TGI of 50% and 41% when 60 mg/kg agent was given by gavage twice a day." (PMID 34503063, 2021). "Targeting residual PRC2 activity with EZH2 inhibitors to switch on tumour suppressor and pro-differentiation genes is another plausible avenue for DMG treatment." (PMID 34944870, 2021). "As expected, disruption of EZH2 or HOTAIR increased the sensitivity of tumor cells to T cell killing." (PMID 34887871, 2021). "Based on H3K27me3-mediated gene expression silencing, EZH2 often functions as a transcriptional repressor to downregulate tumor suppressors such as ADRB2 and DAB2IP." (PMID 35059393, 2021).
tumor (continued). "The EZH2 appearance suppression was highest in the U87 tumor treated with 5 mM of NaDCA and 5 mM of MgDCA, sequentially 8.3- and 20.5-times, while in the PBT24 tumor the preparations reduced EZH2 expression by 3.8- and 4.0-times, respectively." (PMID 33716589, 2021). "Regarding the roles played by EZH2 in the pathogenesis of CM, several mechanisms by which it supports tumor growth and metastasis have been proposed." (PMID 34575678, 2021). "Further treatment with oe‐EZH2 increased the tumour volume in mice and led to a notable upregulation in the expression of EZH2." (PMID 34510715, 2021). "The involvement of EZH2 in tumor development and progression has been investigated in different tumors, including MCPyV-driven MCC." (PMID 34768895, 2021). "To corroborate these observations, we evaluated the expression of the cell cycle inhibitor p21 in tumor cells by RT-PCR, and we confirmed that Mo-TAMs were able to fully revert the p21 induction triggered by EZH2 inhibition." (PMID 33922336, 2021). "Proximal tumor-gained promoters (‘gained.TSS’ regions) significantly enriched with EZH2 (p-value < 1.6 × 10–16, Fisher’s exact test) and SUZ12 (p-value < 3.5 × 10–15, Fisher’s exact test) binding sites." (PMID 33916417, 2021). "In keeping with the effect of EZH2 inhibition in tumor cells, Mo-TAMs from EPZ-6438-treated MCS also showed a significantly enhanced expression of CCL2 and VEGF, thus suggesting a potentiation of the circuits favoring TAM accumulation." (PMID 33922336, 2021). "Here, we performed a comprehensive analysis of data in the genomic and transcriptomic (cBioPortal, KMplot) database portals of clinical tumor samples and evaluated clinical correlations of EZH2, SUZ12, and EED." (PMID 34202528, 2021). "Generally, PTEN staining decreases in tumor versus adjacent normal, and EZH2 staining increases, though the magnitude of the changes between tumor and normal varies between cases." (PMID 33750924, 2021). "Whilst re-expression of EZH2 has a tumour suppressor effect in myeloid malignancies, it is the depletion of EZH2 in PDAC that is associated with conversion towards the less aggressive, classical molecular subtype." (PMID 34680285, 2021). "EZH2 is also capable of recruiting DNMT1 in many cell types to methylate the promoter regions of various genes including tumor suppressors." (PMID 33572395, 2021). "A recent study found that inhibiting the enzymatic activity of EZH2 can promote the transition from H3K27me to H3K27ac, which in turn leads to resistance of some tumor cells to EZH2 inhibitors." (PMID 33794893, 2021). "The results showed that EZH2 was highly expressed in the outer layers of tumor tissues, while GLS was highly expressed in the inner layers." (PMID 34671029, 2021). "ERG together with co-repressors, like HDACs and EZH2, modulates AR transcriptional activity, impeding epithelial differentiation and contributing to tumor progression." (PMID 34230470, 2021). "In vitro and in vivo inhibition of EZH2 attenuated endothelial tubule formation, tumoral migration and invasion, resulting in generally reduced tumor growth." (PMID 34552922, 2021). "The result showed that EZH2 was highly expressed in the nucleus of the tumor tissue compared with adjacent normal tissue." (PMID 33791221, 2021). "EZH2-mediated H3K27 methylation can also silence many tumor suppressors, leading to tumorigenesis and poor prognoses." (PMID 34692550, 2021). "Treatments based on the EZH2 inhibitor, DZNep, enhanced the effect of gemcitabine in tumor-derived cell lines and primary cultures from PDAC." (PMID 34198989, 2021). "Recently, EZH2 was shown to affect tumor cell metabolism, including carbohydrate metabolism, amino acid metabolism, and lipid metabolism." (PMID 35004688, 2021). "The results of our study suggest that circGSK3B functions as a tumor suppressor by inhibiting EZH2-induced histone trimethylation." (PMID 34666800, 2021).
tumor (continued). "The SNHG20/EZH2/E-cadherin pathway was also identified as the potential mechanism in promoting tumor progression and epithelial-mesenchymal transition." (PMID 34888264, 2021). "The enhancer of zeste homologue 2 (EZH2) is a histone H3 lysine 27 methyltransferase that promotes tumorigenesis in a variety of human malignancies by altering the expression of tumour suppressor genes." (PMID 33277782, 2021). "To evaluate the expression of EZH2 in PanNEN tissues we performed immunohistochemistry (IHC) on a tumor microtissue collective of 172 patients who underwent surgery for PanNENs." (PMID 34638497, 2021). "Generally, chemical inhibition of EZH2 by an inhibitor will influence both tumor and immune cells in different aspects, including proliferation, apoptosis, metabolism, and cytokine as well as chemokine production." (PMID 34737746, 2021). "Additional studies are needed to confirm the effect of EZH2 on T cell activation in the tumor microenvironment." (PMID 34737746, 2021). "High expression of EZH2 in OC promoted cell proliferation and correlated with a high proliferative index and tumour grade in OC." (PMID 33336896, 2021). "The appearance of the marker in the tumor is shown in the images, which corresponds to the mean of the EZH2-positive cells of the study group." (PMID 33716589, 2021). "The increase of H3K27Me3 and its corresponding histone-modifying enzymes EZH2, have been described in tumor tissues from CRC patients relative to their normal counterpart, and have been associated with better prognosis." (PMID 33790358, 2021). "In line with the in vitro results, we observed that knockdown of EZH2 alone significantly inhibited tumor growth." (PMID 34175897, 2021). "Database prediction and luciferase reporter gene system proved that hsa_circ_0020123 can promote tumor metastasis through the miR-144-ZEB1/EZH2 axis." (PMID 34788230, 2021). "In different cancer cell types, EZH2 inhibition increases Th1-recruiting chemokines expression, thereby shaping the composition of the tumor immune infiltrate." (PMID 33922336, 2021). "Preclinical studies showed that EZH2 is also involved in regulating tumor growth, invasion and metastasis through H3K27me3." (PMID 34680389, 2021). "Targeting EZH2 represents a way of restoring AR signaling in neuroendocrine-differentiated tumor cells." (PMID 35186711, 2021). "EZH2 expression in PanNENs increased with tumor grade and the majority of PanNECs showed positivity in more than 60% of tumor cells." (PMID 34638497, 2021). "Tumour suppressor function of EZH2 was identified as an interaction partner with MLL-AF9/AML1-ETO9a AML." (PMID 34065087, 2021). "The abnormal expression of PcG was related to the occurrence and development of tumor closely, and EZH2 is the core component." (PMID 34381492, 2021). "In total, in 10 tumor types, the higher expression of at least one of the EZH2, SUZ12, or EED genes was significantly correlated with poor prognosis (logrank p < 0.05)." (PMID 34202528, 2021). "This would mean that the cancer of the adult U87 cell line in terms of EZH2 appearance is more sensitive to the treatment with MgDCA than the pediatric PBT24 cell line tumor." (PMID 33716589, 2021). "Through this physical and functional interaction, ERG and EZH2 cooperatively activate a network of genes sustaining tumor progression and castration resistance." (PMID 34230470, 2021). "Consistently, the tumor weight in the EZH2 knockout group was lower than in the control and WT groups." (PMID 34815475, 2021). "This led to an elevation in RORA expression and the suppression of tumor progression, revealing the critical roles of circGSK3B and EZH2 in GC progression." (PMID 34666800, 2021). "For example, curcumin, sulforaphane, tanshindiols, rottlerin, and other plant extracts exhibit EZH2 inhibitory activity, which in turn inhibits histone methylation and attenuates tumor proliferation and invasion to induce cellular apoptosis." (PMID 34001246, 2021).
tumor (continued). "IHC staining confirmed a strong decrease of EZH2 levels in surviving tumor cells during the acute phase of the treatment (Group 2) compared to the untreated control group (Group 1)." (PMID 34845197, 2021). "Unlike other studies reporting that miR-144/miR-451a suppress proliferation of HCC cells by targeting oncogenes like EZH2, we found that these miRNAs exert a tumor-suppressive role mainly through remodeling the tumor immune microenvironment." (PMID 33658044, 2021). "miR-101 downregulates EZH2 and was thus overexpressed to investigate new tumor suppressor miRNAs potentially repressed by EZH2." (PMID 33728560, 2021). "The majority of CRC biopsies displayed PRMT5- and CDKN2B-positive staining in both cytoplasmic and nuclei of tumor cells, whereas EZH2 was apparently expressed in the nuclei of tumor cells." (PMID 33664859, 2021). "Inhibition of EZH2 in vitro in PanNEN cell lines and in patient-derived islet-like tumoroids reduced cell viability and impaired cell proliferation, while inhibition of EZH2 in vivo in Rip1TAG2 mice reduced tumor burden." (PMID 34638497, 2021). "Infigratinib-resistant tumours exhibited higher levels of p-ErbB2 and p-ErbB3, concomitant with an increase in EZH2 expression." (PMID 34156519, 2021). "The analysis of tumor subtypes revealed a distribution of alterations in the EZH2, EED, and SUZ12 genes (amplifications, deep deletions, mutations, fusions, and multiple alterations) in the 20 most common tumor subtypes (at least 50 samples per each subtype)." (PMID 34202528, 2021). "Tumor-infiltrating Tregs are dependent on EZH2, an epigenetic switch, to maintain Treg stability and function." (PMID 33717139, 2021). "Inhibition of EZH2 by small molecular inhibitors or gene knockdown results in reduced cancer cell growth and tumour formation." (PMID 33277782, 2021). "The EZH2 levels in various tumor types and the correlations between EZH2 levels and overall survival and disease-free survival were reanalyzed." (PMID 34381816, 2021). "Tumor-associated genes on Chr9q such as FANCC, NTRK2, SYK, and NOTCH1 were amplified; amplification of BRAF, EZH2, MET, CDK6 and HGF located on Chr7 were also detected." (PMID 34895266, 2021). "More importantly, chemotherapeutic agents combined with the EZH2 inhibitor tazemetostat reversed chemotherapy-elicited exosome-induced drug resistance in a nude mouse tumor xenograft model." (PMID 33823894, 2021). "circ_0115744 was identified as a tumor-promoting noncoding RNA in CRC through the miR-144/EZH2-dependent mechanism." (PMID 33591945, 2021). "A small molecule inhibitor of EZH2 drove intratumoral Tregs to acquire pro-inflammatory functions, leading to remodeling the tumor microenvironment and enhancing the anticancer immunity without provoking systemic autoimmunity." (PMID 33717139, 2021). "Enhancer of zeste homolog 2 (EZH2) is a classical epigenetic regulator of tumor genesis, metastasis, and prognosis." (PMID 33761979, 2021). "EZH2 inhibitors (EZH2i) have been shown to reduce tumor growth and promote apoptosis and autophagy in preclinical models across different tumor histologic types characterized by the presence of EZH2-activating mutations or altered EZH2 expression." (PMID 34349608, 2021). "GSK126 significantly reduces the level of H3K27me3 in tumor cells by inhibiting the methyltransferase activity of EZH2, thereby inhibiting the growth of tumor cells such as human tongue squamous cell carcinoma and multiple myeloma cells." (PMID 34737956, 2021). "In terms of anti-tumor immunity, EZH2+CD8+ T cells are often void of dysfunction markers (KLRG1, Tim-3, CD57), and the EZH2+CD8+ T cell population positively correlates to anti-tumor response." (PMID 35087832, 2021). "Those events establish a positive feedback loop which improves the activity of EZH2 and favors tumor progression." (PMID 34072826, 2021). "The high expression of EZH2 in cells is closely related to the progression, invasion, and metastasis of neoplasm." (PMID 34737956, 2021).
tumor (continued). "Targeted disruption of EZH2 in regulatory T cells enhances the anti-tumor immune response in mouse models." (PMID 34001289, 2021). "It was also shown that EZH2 is overexpressed in OSCC cell lines and primary tumours, and that a genetic or pharmacological inhibition of EZH2 attenuates tumour growth and restores differentiation gene expression in differentiation refractory OSCC xenografts." (PMID 34680271, 2021). "We found that EZH2 expression in tumor tissues of DLBC, LGG, OV, SARC, THYM, and UCS was higher than the corresponding control tissues (P < 0.05); the expression of EZH2 in tumor tissues of LAML was lower than the corresponding control tissues (P < 0.05)." (PMID 34381492, 2021). "We found that increased expression of the methyl transferase EZH2 correlated with higher tumor grade and advanced disease status." (PMID 34638497, 2021). "In lung cancer, cells that highly express LAT1 show increased abundance of SAM, improving the activity of the histone methyltransferase EZH2 and consequently, increasing H3K27me3 levels to enhance subcutaneous tumor growth." (PMID 35004688, 2021). "Considered a tumor suppressor, EZH2 plays a role in silencing CDH1, FOXC1, DAB2IP, and TIMP3, events linked to metastatic progression." (PMID 34680307, 2021). "The relative expression levels of EZH2 mRNA and protein in tumor cells were up-regulated, which were similar to those observed in the bioinformatics analysis." (PMID 34381492, 2021). "The EZH2 knockout group showed a significant suppression of tumor growth compared to the control and WT groups (p < 0.001)." (PMID 34815475, 2021). "In the context of tumor immunology, the function of EZH2 in Tregs was investigated by Dupage and Sharma, respectively." (PMID 33403469, 2021). "Significantly higher protein expression of EZH2 was also observed for patients with T3–T4 tumor stage compared to those with T1–T2 (p = 0.004) as well as in presence of nodal (p = 0.008) and distant metastases (p < 0.001)." (PMID 34638497, 2021). "The EZH2-positive cell number in the U87 tumor decreased the most with 5 mM NaDCA and 5 mM MgDCA treatment by 8.3- and 20.5-fold, respectively, while in the PBT24 tumor by 3.8- and 4.0-fold, respectively." (PMID 33716589, 2021). "It showed that the tumor size and tumor weight was obviously decreased after EZH2 knockdown while the decreased tumor size and tumor weight was recovered by WT STAT3 overexpression." (PMID 34335938, 2021). "Elevated EZH2 expression is well recognized in a wide range of cancers, including PTC, and its expression is strongly linked to tumor malignancy, invasiveness, and poor prognosis." (PMID 34811354, 2021). "The tumor suppressive effects be realized through selective repression of H3K27me3 by concentration-dependently blocking the EZH2/EED axis and diminishing EZH2 levels." (PMID 33882457, 2021). "The EZH2 inhibitor tazemetostat moderately impacted the syngeneic xenografts tumor growth and enhanced the efficacy of taxane chemotherapy significantly reducing overall tumor size and increasing intratumoral T cells." (PMID 34725325, 2021). "Our findings revealed the downregulation of miR-137 in ESCC and its tumor suppressive role by targeting EZH2 and PXN." (PMID 33685449, 2021). "Reversing EZH2 epigenetic programing to de-repress antigen presentation and tumor cell STING expression represents one promising approach." (PMID 33578789, 2021). "Since the hub genes in the IPA network were AURKA and EZH2, we further validated the role of AURKA and EZH2 in tumor cell proliferation and migration in HCC cell lines." (PMID 35059393, 2021). "The opposite role of EZH2 in PFAs—whereby it is globally repressed, although its residual activity is essential for tumor development—calls for preclinical and clinical testing of EZH2 inhibitors as potential therapeutic interventions in PFA EPN." (PMID 34885210, 2021).